IL10 (interleukin 10)
Diseases named in the same sentence as IL10 in open-access papers (continued):
Sharing a sentence is not in itself a finding about the gene and the disease.
neuroblastoma (19 papers, 2013 to 2025). Neuroblastoma (NB) is the most common solid, extracranial childhood tumor. "On the other hand, we also found significant associations between low serum levels of IL-10 and TGF-β and a decreased risk of developing INSS stage 1 and 2 neuroblastoma tumors." (PMID 40722593, 2025). "In human cells, treatment of SH-5Y5Y neuroblastoma cells with corticosterone decreased autophagy function, which led to increased IL-6 and IL-10 production, although the mechanisms are unclear." (PMID 39639175, 2025). "This study has also identified that neuroblastoma patients with an age of ≥18 months had higher expression of inflammation-related genes (IL10, IL6R, CD16, CD33, and FCGR3), as compared to patients diagnosed at age ≤ 18 months." (PMID 32722460, 2020). "Surprisingly, IFN-γ was found to suppress the expression of B7-H6 and BAT3 mRNA, whereas IL-10 increased B7-H6 mRNA expression on neuroblastoma tumors." (PMID 28424697, 2017). "We compared gene expression of neuroblastoma tumors and cell lines using a TLDA assay and found that tumors have higher expression of TAM-associated genes as well as of IL-6 and IL-10 than cell lines." (PMID 23982484, 2013). "Similar to our findings, neuroblastomas treated with the boiling form of histotripsy (boiling histotripsy) demonstrated greater PDL-1 expression within the TME and decreased IL-10 and increased IFNγ systemic concentrations." (PMID 37893110, 2023). "PS suppressed the levels of IL-6, IL-10, CXCL1, and CXCL2 induced by paclitaxel in a neuroblastoma cell line, and macrophage activation to the M1 proinflammatory phenotype." (PMID 38347876, 2023). "This was attributed to the neuroblastoma cell line secreting factors such as transforming growth factor-β (TGF-β) and IL-10, which decreases T cell cytotoxicity, whereas select studies have shown IL-10 to increase NK cell activity in vivo." (PMID 33803078, 2021). "The cytokines IFN-γ, IL-2, IL-7, IL-12, IL-15, IL-18, IL-21, and IL-27, promoted neuroblastoma regression via enhancing the efficacy of effector cells, whereas VEGF, IL-6, and IL-10 induced neuroblastoma progression through their immunosuppressive activities." (PMID 33322408, 2020). "In neuroblastoma SH-SY5Y cells, previous studies observed that LPS treatment resulted in the enhanced synthesis of proinflammatory cytokines like TNF-α, IL-1β, and IL-6, while there was a decrease in anti-inflammatory cytokines like IL-10." (PMID 38671881, 2024). "In vitro, neuroblastoma-exposed monocytes/macrophages upregulated M2 markers (CD163, CD204, IL-10)." (PMID 38087370, 2023). "In co-cultured murine neuroblastoma and microphage cell lines (Neuro-2A and RAW264.7) that mirror the inflammatory infiltrate of CIPN, we evaluated the effect of PS on the expression of four cytokines, IL-6, IL10, CXCL-1, and CXCL-2, all involved in CIPN." (PMID 38347876, 2023). "Therefore, it is crucial to study the role and effect of anti-inflammatory cytokines such as IL-10 and TGF-β in various tumors such as Neuroblastoma, because the development of immunotherapeutic drugs to combat immunosuppression within the tumor environment is currently of great importance." (PMID 40722593, 2025). "In addition to inhibitory signals, the availability of soluble factors in the TME, including galactin 1 and 3, TGF-β, and IL-10, can trigger T cell inhibitory pathways or inhibit T cell function, while secretory HMGB1 may be responsible for Treg differentiation in the neuroblastoma TME." (PMID 33322408, 2020).
Q fever (19 papers, 2010 to 2025). A bacterial infection caused by Coxiella burnetii. "IL-10 production by peripheral blood mononuclear cells from patients with Q fever endocarditis and Q fever with valvulopathy who were at risk for developing chronic Q fever was high, compared to control individuals." (PMID 35137689, 2022). "Up-regulation of the IL-10 and Stat-3 genes may account for the high susceptibility of men with Q fever to C. burnetii infection and autoantibody production." (PMID 20730052, 2010). "IL-10 overproduction is seen in the serum of chronic Q fever, where patients present with persistent focalized infections that are more severe than the initial acute infection." (PMID 40586810, 2025). "From an immunological point of view, chronic Q fever is marked by elevated inhibitory cytokines, mainly IL-10." (PMID 40559597, 2025). "An important role of IL-10 in chronic development of Q fever has been postulated based on converging evidence from a series of in vitro studies." (PMID 35137689, 2022). "The microbicidal activity of monocytes from patients with chronic Q fever was restored by neutralizing IL-10." (PMID 35137689, 2022). "Defective phagosome maturation and impaired C. burnetii killing were induced by interleukin (IL)-10 addition to monocytes from convalescent patients and were restored by IL-10 neutralization in chronic Q fever in evolution." (PMID 34796128, 2021). "Experimental studies in human and mouse cells correlate defective monocyte/macrophage activation and migration with ineffective granuloma formation, and overexpression of interleukin (IL)-10 is present in patients with chronic Q fever." (PMID 33789347, 2021). "Some studies show that the clinical manifestations of persistent Q fever are associated with an altered Th1 response with a defective production of IFN-γ and an overproduction of IL-10." (PMID 32765448, 2020). "In Q fever, overproduction of interleukin-10 (IL-10) by infected monocytes was found critical in both sustaining replication of the C. burnetii and preventing the macrophages microbicidal activity." (PMID 31293984, 2019). "The role of IL-10 is demonstrated in transgenic mice that constitutively overexpress IL-10 in the macrophage compartment and exhibit sustained infection, as in chronic Q fever." (PMID 25346736, 2014). "The role of IL-10 in the pathogenesis of chronic infection is strengthened by the correlation of the amount of IL-10 and the chronic evolution of Q fever with the restoration of the microbicidal competence of monocytes when IL-10 was neutralized." (PMID 25346736, 2014). "In mice as well as in humans persistent Coxiella presence seems to be IL-10 dependent and humans suffering from chronic Q fever excrete high levels of IL-10." (PMID 23915213, 2013). "Additionally, the secretion of IL-10 by monocytes has been identified as a significant driver of chronic Q fever, with studies in mouse models further confirming the critical role of IL-10 in the persistence of C. burnetii." (PMID 41468478, 2025). "Overall, IL10 and Th2 cytokines seem to interfere negatively with the control of Q fever." (PMID 36788233, 2023). "Finally, low IL-10 production in monocytes from patients with acute Q fever was associated with C. burnetii elimination, whereas C. burnetii replicated in monocytes from patients with chronic Q fever and high IL-10 production." (PMID 35137689, 2022). "It has been suggested that IL-10 overproduction promotes progression to chronic Q fever." (PMID 34796128, 2021). "This latter program is characterized by the low production of inflammatory cytokines and the overproduction of immunoregulatory cytokines, such as interleukin (IL)-10, which is associated with persistent infection in tissues from mice overexpressing IL-10 and persistent Q fever in humans." (PMID 32765448, 2020).
Q fever (continued). "In addition, mice overproducing IL-10 from macrophages have higher and prolonged bacterial burden after infection with C. burnetii, constituting a mouse model for chronic Q fever." (PMID 30800124, 2019). "In patients with chronic Q-fever, the anti-inflammatory cytokine IL-10 is up-regulated." (PMID 25279829, 2014). "Q fever patients with hepatitis show serum cytokines levels higher than those affected by pneumonia or fever, and TNF and IL-10 are increased in patients with valvulopathy and extremely high in case of endocarditis." (PMID 34796128, 2021). "Other cytokines also play a role in Q fever as TNF-α, IL-1-β, and IL-10 as well as IL-2 and the IL-12/IFN pathway does play a role." (PMID 32765448, 2020). "The release of IL-10 by control PBMCs stimulated with BCG- or CB-coated beads did not exceed 40 pg/ml in healthy controls and patients cured from Q fever." (PMID 27441846, 2016). "We did not expect this, as in humans high IL-10 protein levels are related to chronic Q fever infection, and in acute Q fever patients a slight increase of IL-10 production was observed compared to healthy controls." (PMID 25279829, 2014). "However, the measurement of IL-10 at a given time of Q fever evolution is not sufficient to assess the prognosis of patients with Q fever." (PMID 25346736, 2014).
silicosis (19 papers, 2010 to 2024). Silicosis is a respiratory disease caused by breathing in (inhaling) silica dust. "Additionally, ZC3H4 is a crucial protein associated with silicosis that can regulate IL-10 release by controlling autophagy in monocytes." (PMID 35962397, 2022). "In experimental silicosis, less intense fibrosis in response to silica particles was observed in IL-10 deficient mice when compared with wild-type mice, while the inversed effect has also been observed in the livers of IL-10 deficient mice." (PMID 36311760, 2022). "Moreover, increased levels of TGF-β may be associated with a T regulatory response, because TGF-β and IL-10 secreted by regulatory T cells can suppress Th1 immune response, which leads to a preferential Th2 response in murine silicosis." (PMID 29126438, 2017). "There is clear evidence that IL-10-producing Bregs (B10) are involved in the development of silicosis through the regulation of the Th cell balance." (PMID 38515835, 2024). "The levels of IL-10 and Bregs are increased in patients with silicosis, resulting in Treg maintenance and the regulation of the Th1/Th2 immune balance." (PMID 38515835, 2024). "In silicosis, IL-10 is elevated but has a dual effect: on one side, IL-10 limits the amplitude of the inflammatory response by suppression of the production IL-1β, IL-6 and TNF-α in monocytes and macrophages." (PMID 36672608, 2022). "The TNF-α over IL-10 ratio was evaluated, and the results showed a ratio less than 1 had a protective effect for developing silicosis." (PMID 36672608, 2022). "Contrasting opinions on the exact roles of Th2 cytokines IL-10 and IL-4 in the course of silicosis development have thus far been proposed." (PMID 36311760, 2022). "The fibrogenic activity of macrophage-derived IL-10 and M2-like macrophages is not limited to silicosis." (PMID 34489937, 2021). "In fact, we observed increased IL‐10 levels in the lung tissue of Silicosis‐MT group animals, while there was a significant reduction in IL‐1β and TGF‐β." (PMID 32538526, 2020). "Patients with asbestosis have elevated expression of IL-10 in their AMs, whereas patients with silicosis showed increased levels of IL-10, IL-4, IL-5, and IL13 in their serum." (PMID 32625201, 2020). "In a different study, patients with silicosis were found to have elevated level of plasma IL-10 through a protein array screening of plasma cytokines." (PMID 32625201, 2020). "In this study, we comprehensively showed the role of IL-10-producing regulatory B cell (B10) in a silicosis model of mice." (PMID 27354007, 2016). "With the development of silicosis, T regulatory cells suppress the Th1 immune response by secreting increasing amounts of IL-10 and TGF-β." (PMID 25299237, 2014). "To investigate the mechanism of how Tregs regulate Th17 differentiation in silicosis, we firstly investigated the cytokine IL-10 and TGF-β1: two crucial functional factors secreted by Tregs and played important roles in Th17 generation." (PMID 22615967, 2012). "With the development of silicosis, Treg cells suppress Th1 immune response by secreting increasing amount of IL-10 and TGF-β." (PMID 21072213, 2010). "Furthermore, within groups of diagnosed patients with silicosis, IL-1RA and IL-10 levels were higher in PMF than in SS patients." (PMID 36675056, 2023). "Patients with silicosis also had increased levels of IL-4, IL-5 IL-10, and IL-13 in their serum." (PMID 35547729, 2022). "However, studies have suggested that the long-term release of large amounts of IL-10 exacerbates the progression of silicosis." (PMID 35962397, 2022). "Additionally, research on B cells in silicosis has mainly focused on IL-10 producing regulatory B cells (B10 cells)." (PMID 34149803, 2021). "However, how B cells differentiate into IL-10-producing Bregs and what functions the cells play in silicosis progression remain to be further investigated." (PMID 28243231, 2017).
silicosis (continued). "It is tempting to speculate that B10 might mainly suppress the Th responses by releasing IL-10 in experimental silicosis." (PMID 28831210, 2017). "In this capacity, it is possible that IL-10 downregulation as observed in our study, may limit pulmonary inflammation and subsequently control the extent of collagen accumulation observed in the inflammatory stages of silicosis." (PMID 36311760, 2022). "Consistently, the transcriptomic analysis of patients with advanced silicosis revealed up-regulated expression of IFN-γ, IL-10 and CXCR4, and the OX40L/OX40 signaling pathway." (PMID 34149803, 2021). "RT‒PCR showed that inflammatory cytokines (IL-1β, IL-6 and TNF-α) were upregulated in AMs, but IL-10 expression was not significantly different, which indicated that AMs in the early stage of silicosis were mainly inflammatory macrophages." (PMID 38454505, 2024). "If TNF-α/IL-10 ratio is supraunitary, IL-10 is not able to suppress the pro-inflammatory effect of TNF-α, suggesting that the risk factor for silicosis should be derived from this ratio and not from the independent values of TNF-α and IL-10." (PMID 36672608, 2022). "In contrast, high levels of IL-10 in BAL or serum were detected in patients with silicosis and asbestosis in the absence of clear inflammatory reaction." (PMID 34489937, 2021). "Treg cytokines (TGF-β and IL-10) and Th2 cytokines (IL-4, IL-5, and IL-13), but not Th1 cytokines (IFN-γ, IL2, and IL-12) and pro-inflammatory cytokines (IL-1β, IL-6, and TNF-α), were found to be increased in the sera of patients with silicosis." (PMID 32625201, 2020).
skin cancer (19 papers, 2011 to 2025). "Up to now, a number of studies have been performed to evaluate the effect of common IL-10 polymorphisms on the risk of skin cancer." (PMID 29467923, 2018). "The current study was designed to quantitatively summarize the evidence for the strength of the associations between common IL-10 functional polymorphisms and skin cancer risk." (PMID 29467923, 2018). "It was also notable that IL10−/− mice were found to be particularly susceptible to chemically induced skin cancers, which highlights its protective role." (PMID 30326660, 2018). "The present study based on 26 studies including 4090 cases and 4133 controls was the first article employing a meta-analysis to specify the effect of common IL-10 polymorphisms on susceptibility to skin cancer." (PMID 29467923, 2018). "In the current study, we sought to give a more authentic cognition concerning the associations between the common IL-10 polymorphisms (−1082G>A, −819C>T and −592C>A) and susceptibility to skin cancer by a meta-analysis." (PMID 29467923, 2018). "Recently, we have shown that IL-10 polymorphisms are strongly correlated to sun-related skin cancers in a Japanese population." (PMID 22639094, 2012). "Genetic variations in IL-10 gene may lead to different immune responses and susceptibility to skin cancer." (PMID 29467923, 2018). "The subgroup analysis also presented a reduced skin cancer risk associated with −819 C>T variant of IL-10 in heterozygote model (OR = 0.67, 95CI = 0.50–0.91, p = 0.01) in non-melanoma skin cancer but not in melanoma skin cancer in any genetic model (all p > 0.05)." (PMID 29467923, 2018). "We found that neither −1082G>A nor −592C>A was a conspicuous low-penetrant risk factor for developing skin cancer, However, the results indicated that IL-10 −819C>T variant may contribute, although modestly, to the reduction of skin cancer risk, especially for BCC subtype." (PMID 29467923, 2018). "Given the importance of IL-10 protein which is a multifunctional cytokine with both immunosuppressive and anti-angiogenic functions in cancers, a genetic predisposition concentrating on IL-10 common variants to skin cancer has been suggested by a growing of studies." (PMID 29467923, 2018). "The skin under the influence of UV radiation produces and activates Treg, which inhibits Th1-induced immunity against skin cancer through the production of IL-10." (PMID 33917793, 2021). "Foxp3 mRNA levels were significantly elevated in skin tumors, while IL-10 mRNA levels were significantly elevated in skin tumors, draining lymph nodes, and lung metastatic nodules in CCL17 TG mice." (PMID 33670758, 2021). "IL-10 is a suppressive cytokine that functions by down-regulating excessive inflammatory responses; IL-10 mRNA transcripts have been isolated from tumor tissues including ovarian, breast, renal, lung, and skin cancer." (PMID 31681327, 2019). "In the present study, a potential role of IL-10 −819C>T polymorphism, although modest, in reducing the risk of skin cancer was revealed by pooling 7 individual studies with 862 cases and 957 controls, suggesting that TT genotype may be more protective from the susceptibility to skin cancer." (PMID 29467923, 2018). "UV irradiation induces Treg cell expansion in the skin, whereas Treg suppresses Th1-driven immunity against skin cancer through the production of IL-10." (PMID 31051015, 2016). "However, the adoptive transfer of UVR-induced regulatory T cells from IL-10-deficient mice failed to suppress Th1 responses to skin cancer, suggesting that IL-10 merely limits anti-tumor adaptive immunity during skin cancer development." (PMID 33917793, 2021). "Interestingly, it was demonstrated that omega-3 can increase IL-10 levels in skin cancer and its elevation was able to inhibit the pro-inflammatory cytokines production, leading to reduced tumor growth and progression." (PMID 31374840, 2019).
skin cancer (continued). "The present study suggested a potential association between IL-10 −819C>T polymorphism and decreased risk of skin cancer, but a lack of association for −1082G>A and −592C>A polymorphisms." (PMID 29467923, 2018). "Adoptive transfer of UV-induced regulatory T cells from IL-10-deficient mice failed to suppress Th1 response against skin cancer." (PMID 31051015, 2016). "In recent years, it has been demonstrated that IL-10, which has traditionally been thought to contribute to the immunosuppressive milieu, is required for efficient immunosurveillance of the initiation and progression of skin tumours." (PMID 25162011, 2014). "Hence, strategies based on more comprehensive haplotype or multiple polymorphisms rather than a single polymorphism may provide more precise information on genetic contribution of IL-10 to skin cancer aetiology." (PMID 29467923, 2018). "IFN-γ expression can be induced by IL-10 in CD8+ T cells in skin cancer, suggesting the possible immunological regulation of IDO1 expression through IL-10 and IFN-γ." (PMID 38540186, 2024). "However, IL-10 may contribute to skin cancer development, as IL-10-deficient mice do not develop skin tumors upon UVB exposure." (PMID 30416507, 2018). "In skin cancers, dermal mast cells are able to respond to UVB-induced IL-33 by releasing IL-10 to protect skin homeostasis after excessive UVB exposure." (PMID 30416507, 2018). "Studies in genetically modified mice and in human tumors found that altered expression of selected pro- (MCP-1, IFN-γ) and/or anti-inflammatory cytokines (IL-4, IL-10, and TGF-β1) had a crucial role in the promotion of gastric, colorectal, liver, breast, and skin carcinoma development." (PMID 28053372, 2016).